C1QC (complement C1q C chain)
Diseases named in the same sentence as C1QC in open-access papers (continued):
Sharing a sentence is not in itself a finding about the gene and the disease.
tumor (continued). "Therefore, C1qA, C1qB and C1qC differential expression is closely related to the degree of tumor necrosis, plays a role in inhibiting tumor development to a certain extent." (PMID 34079754, 2021). "Hence, we hypothesized that aberrant signal communication between MFAP5 + fibroblasts and C1QC + macrophages promotes the tumor-invasive phenotype to a certain extent." (PMID 37344903, 2023). "Therefore, we speculated that the high expression of C1QA, C1QB, and C1QC may play a dual regulatory role through anti-tumour immunity and the induction of cancer cell apoptosis." (PMID 36110204, 2022). "Among potential eat-me signals, we found significant overexpression of C1Q complement components C1qa, C1qb, and C1qc, which have been shown to decorate the surface of apoptotic cells to target them for phagocytosis, and of Slamf7, which is involved in phagocytosis of hematopoietic tumor cells." (PMID 36240276, 2022). "In normal tissues, there were few C1QC+ macrophages surrounding MFAP5+ fibroblasts, suggesting that crosstalk between these cell types occurred primarily within the tumor tissues." (PMID 40191203, 2025). "The CosMx data also revealed that C1QC+ macrophages, CCL5+ T cells, and IGHG1+ plasma cells were more abundant near one tumour subclone while COL3A1+ fibroblasts were more abundant near the other." (PMID 38570491, 2024). "Tumor-enriched macrophages (CTSK+ and C1QC+ macrophage) and WNT5A+ inflammatory fibroblast states, which contribute to diverse aspects of tumorigenesis, were also found in the pro-tumorigenic community." (PMID 38744958, 2024). "Of which a proliferative cell lineage named C1QC+MKI67+TAMs was recognized with high immunosuppressive capacities, suggesting it has immune suppression and cell proliferation functions in the tumor niche." (PMID 39323622, 2024). "In our study, four macrophage subsets were identified in primary tumor and metastatic specimens: SPP1+ macrophages, C1QC+ macrophages, CXCL10+ macrophages and FOLR2+ macrophages." (PMID 38519500, 2024). "Comparison of the gene expression of TREM2+ TAMs between the tumor and adjacent normal tissue revealed that TREM2, SPP1, APOE, C1QA, C1QB, and C1QC were upregulated in tumors, which was consistent with the results for GSE160269." (PMID 37187751, 2023). "Our results revealed several tumor-specific signals between MFAP5 + fibroblasts and myeloid cells, particularly C1QC + macrophages." (PMID 37344903, 2023). "In contrast, there were few C1QC + macrophages around the MFAP5 + fibroblasts in normal tissues, suggesting that crosstalk between these cells mainly occurred in tumor tissues." (PMID 37344903, 2023). "Macrophage clusters from different tumor types were diverse; additionally, SPP1+, C1QC+, ISG15+, and FN1+ TAMs were primarily enriched at the tumor site." (PMID 35504878, 2022). "As revealed from the results, Apoe deletion was correlated with a decline of C1QC + and CCR2+ macrophages in tumor infiltration." (PMID 36147474, 2022). "We selected four hub genes, LAPTM5, C1QC, CSF1R, and SLCO2B1, and analyzed their correlation with the tumor infiltration of 22 immune cell subsets using CIBERSORT and the prognosis of different immunity-related LUSC patient subtypes." (PMID 33428598, 2021). "The CIBERSORT algorithm was applied to analyze the proportions of tumor-infiltrating immune subsets to further confirm the correlations between the TME and C1qA, C1qB, and C1qC expression levels." (PMID 34079754, 2021). "The results showed that the expression of C1QC, FN1, and SPP1 increased significantly in TAMs, which indicated that the tumor microenvironment most likely induced their high expression in macrophages." (PMID 34804043, 2021). "The levels of eight genes (SPI1, RNASE6, C1QB, C1QC, CSF1R, C1QA, TBC1D2, and ATP6V0E1) expression were higher in tumor samples from UALCAN." (PMID 32038997, 2019). "In both the LN and tumor, colocalization of the CD74, C1QC, and CXCL13 mRNAs was observed." (PMID 39312471, 2024).
tumor (continued). "We also suggest CAFs secreted CSF1 or FN1 could unidirectionally target cDC2, C1QC+TAMs, and SPP1+TAMs to promote macrophage or cDCs differentiation, as well as tumor development." (PMID 39323622, 2024). "This is in agreement with our own results, where upregulation of C1QA, C1QC, and CFHR2 in newly diagnosed PCa patients is suggestive of the involvement of tumour inflammatory microenvironment, which may act as a mediator of tumour progression and angiogenesis." (PMID 36831393, 2023). "Intercellular interaction analysis suggested that MFAP5 + fibroblasts could reciprocally communicate with C1QC + macrophages and other myeloid cells to remodel unfavorable conditions via MIF/CD74, IL34/CSF1R, and other tumor-promoting signaling pathways." (PMID 37344903, 2023). "Moreover, the transcriptomes of the VCAN+ TAMs and C1QC+ TAMs showed gradual differences, suggesting that VCAN+ TAMs were reprogrammed into C1QC+ TAMs in the tumor region." (PMID 37383234, 2023). "Single-cell dataset revealed an enrichment of multiple efferocytosis-related genes in distinct myeloid subsets within the tumor, specifically, SPP1+, ISG15+, C1QC+ macrophages, and CD14+ monocytes in the tumors, which were distinct from the scRNA-Seq from the peripheral blood." (PMID 36439171, 2022). "The tumor angiogenesis, cell migration, ECM receptor interaction, and tumor vasculature pathways were enriched in SPP1+ TAMs, whereas the complement activation and antigen processing and presentation pathways were significantly enriched in C1QC+ TAMs." (PMID 34295336, 2021). "Based on these findings, we proposed that LAPTM5, CSF1R, SLCO2B1 and C1QC are mainly expressed in immune cells rather than LUSC cells in tumor samples." (PMID 33428598, 2021). "iCAFs are enriched at the liver site and the tumor-liver interface, ECM CAFs with C1QC+ and inflammatory IL1B+ macrophages at the tumor-liver border and in the tumor site, whereas myofibroblasts and immunosuppressive SPP1+ macrophages infiltrate the tumor core." (PMID 40393458, 2025). "The macrophage lineage was further divided into predominant populations: suppressive (SPP1+, APOC1+), pro-tumour (VEGFA+, MKI67+), inflammatory (C1QC+), classical (CD14+) and non-classical cells (CD16+)." (PMID 39788719, 2025). "Significantly reduced C1qa expression, but not C1qb and C1qc expression, was observed in both MPE and tumor tissue of KO mice, indicating effective C1qa disruption in C1qa-/- mice." (PMID 39664577, 2024). "C1QC+ and SPP1+ TAMs gene signatures, but not M1/M2 gene signatures, can divide cervical patients into subgroups with different prognosis, tumor stage, different immune cell infiltration, and ICMs expression." (PMID 34295336, 2021).
cancer (25 papers, 2019 to 2025). A tumor composed of atypical neoplastic, often pleomorphic cells that invade other tissues. "In conclusion, the current study showed that C1QA, C1QB, and C1QC were highly expressed in a variety of cancers, especially in SKCM, which overexpressed these three complement components and predicted better survival prognosis." (PMID 36110204, 2022). "In the present study, we used the GEPIA database to conduct pan-cancer analysis on the transcription levels of C1QA, C1QB, and C1QC and screened out the cancer types with the differential expression of these three genes." (PMID 36110204, 2022). "ISG15+ and C1QC+ macrophages also mobilized signaling cascades related to carcinoma and T cell exhaustion respectively." (PMID 36439171, 2022). "The C1QA, C1QB, and C1QC genes were either over-expressed, or downregulated depending on the type of carcinoma investigated, as compared to their normal tissue counterparts." (PMID 31130944, 2019). "The expression of C1QA, C1QB, and C1QC genes was analyzed between different carcinoma and normal tissue counterparts using the Oncomine database." (PMID 31130944, 2019). "The 8 cell types were annotated based on the differentially expressed markers: Bnip3 for autophagic cancer cells, Mki67 for proliferating cancer cells, Cd14, Apoe, C1qc, Mrc1, Lyz2 for monocytes, Col3a1 for fibroblasts, Cd3e and Gzma for T cells, Flt1 for endothelial cells, and Klk1 for DCs." (PMID 38802348, 2024). "Accordingly, C1QC expression level was quite different in distinct cell types with the highest in macrophages instead of KIRC cells, suggesting that C1QC may also play its role in immune cells besides cancer cells." (PMID 36992705, 2023). "While C1QC+ TAMs preferentially express phagocytosis- and antigen presentation-related genes, SPP1+ TAMs have a proangiogenic signature and are more likely to engage in crosstalk with cancer-associated fibroblasts (CAFs) and endothelial cells." (PMID 37090726, 2023). "In addition, the mRNA data in the Cancer Cell Line Encyclopedia database showed that the expression of C1QC, CSF1R, LAPTM5 and SLCO2B1 mRNA was significantly lower in LUSC cell lines (n=23) compared to lymphoid cell lines (n=167)." (PMID 33428598, 2021). "We found that 30 of these genes which included Nckap1l, Ncf1, Pla2g15, Unc93b1, Lrrc33, Rgs10, Gmfg, Rbm25, C3ar1, Ccdc88b, Fam105a, Gng11, Phc1, Rasa4, Dag1, Tyrobp, Tmsb4x, Cfp, Prkd1, Gp49a, Trem2, C1qc, Lyz2, Igfbp7, Rab30, Cxcl16, Egfl7, Ube2r2, Pltp, and Cfb, showed a relation with cancer." (PMID 32812032, 2020). "Interestingly, the expression of CD206, CD86, CCR2 and C1QC expression in the Apoe-/- mice non-cancer model compared with Apoe+/+ mice was also decreased, indicating that changes in macrophages in the spleen and TAM might be consistent." (PMID 36147474, 2022). "Eight proteins (C-reactive protein, AGRN, XPOT, LDHA, C1QC, ORM1, ANGPTL4, and prostaglandin D2 synthase [PTGDS]) exhibited a continuously upward or downward trend in three or more cancer types." (PMID 39884577, 2025). "Among these cell type markers of cell clusters, cancer cell cluster specifically expressed keratin 19 (KRT19) and CEA cell adhesion molecule 1 (CEACAM1), and TAM cluster expressed CD68, CD163, and complement C1q C chain (C1QC)." (PMID 38302412, 2024). "C1QC+ TAMs and SPP1+ TAMs have also been identified in PDAC, and were found to share similar characteristics with those in other human cancers." (PMID 39507421, 2024). "In addition, immunohistochemistry was used to confirm that the expression of C1QC and CCR2 in tissues of the three cancer models with Apoe-/- mice were significantly decreased." (PMID 36147474, 2022). "Additionally, we found that TUBA1B+ TAMs, C1QC+ TAMs and IL1B+ TAMs were predominant in early-stage tumors, whereas VCAN+ TAMs, SLC40A1+ TAMs and APOC1+ TAMs had higher proportions in patients with advanced cancer." (PMID 39232806, 2024).
cancer (continued). "We also determined that TREM2+ TAMs highly expressed soluble factors such as SPP1, APOE, C1QA, C1QB, and C1QC, which suggested that this TREM2+ TAMs subset may be exocrine or paracrine for establishing the microflora critical for cancer cell invasion and the metastasis environment." (PMID 37187751, 2023). "In addition, cancer-cell-intrinsic inflammatory tumor subclusters also showed an upregulation of C1R (log2FC = 0.86), C1S (log2FC = 0.46), and C3 (log2FC = 0.48), while the corresponding macrophages showed an upregulation of C1q genes (C1QA, C1QB, C1QC)." (PMID 36973268, 2023).
infection (10 papers, 2012 to 2025). The state of being infected such as from the introduction of a foreign agent such as serum, vaccine, antigenic substance or organism. "Next, involvement of complement genes vital in phagocytosis (C1QA, C1QB, C1QC, C1R), which play a central role in immunity, response to infection, as well as synaptic pruning, further implicate the involvement of the immune system in ASD." (PMID 36590292, 2022). "We found collectively among SP-A variants several genes such as AKT1, BTK, CCL9, PPARG, and RELA to exhibit higher expression in females, whereas, CFLAR, C1QC, LSP1, CKAP2, KAT2B, TACC2, and RCC2 exhibited higher expression in males after infection." (PMID 32670284, 2020). "However, in response to infection, male mice exhibited higher expression levels of CFLAR, and FKBP5 (KO, 1A3), AKT1, and CCL9 (1A3, 6A2), C1QC (6A2), LSP1 (1A3, 6A2, and 6A4), CKAP2, and KAT2B (KO), TACC2 (1A0), RCC2 (1A3, 6A2), PPARG (1A3, 6A4), and ERP44 (6A2) compared to females." (PMID 32670284, 2020).
neurodegenerative disease (2 papers, 2023). A disorder of the central nervous system characterized by gradual and progressive loss of neural tissue and neurologic function. "Decreased expression of pro-inflammatory genes, which are associated with neurodegenerative disease or astrocyte and microglia phenotypes Cd40, C1qB, Cd68, Cd45, Aqp-4, Il1α, Fkbp5, Ggta1, Cd16, H2-T23, and Serping1, was observed following C-32:6 treatment and C1qC, Tspo, and Gbp2 with FFA C-34:6." (PMID 37740008, 2023).
C1QC also shares sentences with these, for which no sentence is quoted: diabetes (3 papers); ovarian carcinoma (3); lupus erythematosus (2); systemic lupus erythematosus (2); Amoebiasis (1); autoimmune thyroid disease (1); C1Q deficiency (1); Cognitive impairment (1); diabetic nephropathy (1); dilated cardiomyopathy (1); endometrial cancer (1); Erythema (1); esophageal cancer (1); gastric cancer (1); head and neck cancer (1); keratitis (1); leiomyoma (1); liver fibrosis (1); lung adenocarcinoma (1); lymphoma (1); mesothelioma (1); metastatic tumors (1); mood disorder (1); neuropathic pain (1); peripheral T-cell lymphoma (1); pertussis (1); preeclampsia (1); Primary immunodeficiency (1); prostate carcinoma (1); Rett syndrome (1).
A further 6 diseases each share a sentence with C1QC in 1 paper.